Y_RNA (Y RNA )
Gene: Miscellaneous RNA gene on chromosome 1 (12,024,012 to 12,024,124, reverse strand). Ensembl gene ENSG00000202461.
Homologues: Orthologues: chimpanzee Y_RNA (98% identical). Paralogues in human: Y_RNA (75% identical), Y_RNA (74% identical), RNY1 (73% identical), RNY1P16 (73% identical), Y_RNA (73% identical), Y_RNA (72% identical), Y_RNA (71% identical), Y_RNA (70% identical), Y_RNA (69% identical), RNY1P5 (68% identical), RNY1P8 (68% identical), Y_RNA (68% identical), and 87 more.